PFKFB4 (6-phosphofructo-2-kinase/fructose-2,6-biphosphatase 4)
Diseases named in the same sentence as PFKFB4 in open-access papers (continued):
Sharing a sentence is not in itself a finding about the gene and the disease.
tumor (continued). "The selection of Heme oxygenase-1 (HMOX1) and the enzyme 6-phosphofructo-2-kinase/fructose-2,6-biphosphatase 4 (PFKFB4) as therapeutic targets is grounded in their pivotal roles in promoting tumor progression and treatment resistance." (PMID 40739397, 2025). "Both in vitro and in vivo models demonstrate that inhibiting PFKFB4 can effectively reduce tumor growth and increase the sensitivity of ccRCC cells to treatment." (PMID 40253354, 2025). "Particular attention will be given to PFKFB4-associated signaling pathways, including its interactions with HIF-1α, regulation of glucose metabolism reprogramming, and promotion of tumor stemness properties." (PMID 40269756, 2025). "In vivo experiments in CDX models of luciferase‐labeled FG cells revealed that SP1 and PFKFB4 knockdown also suppressed tumor growth, and the inhibitory effect of SP1 knockdown on tumor growth was rescued by PFKFB4 overexpression." (PMID 40832790, 2025). "PFKFB4 promotes tumor progression and lenvatinib resistance, highlighting its potential as a novel therapeutic target for HCC." (PMID 40269756, 2025). "Previous studies have demonstrated PFKFB4 is markedly elevated in tumor tissue, correlating with aggressive tumor characteristics and adverse outcome." (PMID 40269756, 2025). "Silencing PFKFB4 in ccRCC cells significantly diminishes their proliferative capacity, migration, and wound healing abilities, underscoring its crucial role in tumor progression and metastasis." (PMID 40253354, 2025). "The enzymes of glycolysis can directly interact with the autophagy machinery (HK2) to change their activity or expression levels or to directly induce changes in autophagy in tumor cells (PFKFB4) as an adaption to cellular stress conditions." (PMID 37190124, 2023). "Taken together, knockdown of EZH2 inhibited tumor growth in vivo by mediating the FBXL7/PFKFB4 axis." (PMID 37179372, 2023). "The findings collected from this study supported the promoting effect of hypoxia on the glucose metabolism and tumor growth of NSCLC via regulation of the EZH2/FBXL7/PFKFB4 axis." (PMID 37179372, 2023). "PFKFB4 plays important roles in tumor cell glucose metabolism as it shows more FBPase-2 activity, redirecting glucose to the pentose phosphate pathway, and supporting ROS detoxification and lipid and nucleotide synthesis." (PMID 37179372, 2023). "It was reported that PFKFB4 seems to contribute to tumor growth by regulating G1/0 phase progression for cell proliferation." (PMID 37919747, 2023). "Consistent with our findings above, PFKFB4 expression was upregulated in multiple tumours compared with paracarcinoma tissues." (PMID 36127291, 2023). "In conclusion, our work reveals that the EZH2/FBXL7/PFKFB4 axis plays a regulatory role in glucose metabolism and tumor growth of NSCLC, which is expected to be potential biomarkers for NSCLC." (PMID 37179372, 2023). "PFKFB4 regulates glycolysis in cells by generating the glycolytic signaling molecule F-2,6-BP and subsequently hydrolyzing it, thus limiting tumor development." (PMID 37770581, 2023). "PFKFB4 was mainly expressed in the cytoplasm and nucleus, and it was diffusely distributed in the tumor tissues." (PMID 37770581, 2023). "Overall, our study indicates that hypoxia can promote the glycolysis and tumor growth of NSCLC by regulating the EZH2/FBXL7/PFKFB4 axis." (PMID 37179372, 2023). "PFKFB4 expression in tumor tissues was significantly higher than that in normal tissues (p < 0.001)." (PMID 37919747, 2023). "PFKFB4 is overexpressed in multiple human cancers such as lung adenocarcinoma, supports tumor growth by synthesizing F-2,6-BP and is required for glycolysis in response to hypoxia and tumor growth." (PMID 36059961, 2022). "The levels of glycometabolism-related hub genes (G6PD, CENPA, STC2, and PFKFB4) in tumor samples were higher than those in normal samples (p < 0.001)." (PMID 35938165, 2022).
tumor (continued). "Our earlier findings showed that 5-MPN (a specific PFKFB4 inhibitor) suppresses CD44ICD/PFKFB4-induced tumor development." (PMID 34976184, 2022). "Taken together, the present study demonstrates that the histone modifier KDM3A epigenetically activates SP1 transcription, which further activates the glycolysis-related PFKFB4 in OS, consequently leading to tumor cell growth and metastasis." (PMID 35590288, 2022). "One of the mechanisms through which PFKFB4 facilitates the proliferation and chemoresistance of tumor cells is controlling autophagy." (PMID 36034839, 2022). "Targeting PFKFB3 and PFKFB4 in tumor cells has been shown in a few in vitro studies to inhibit glycolysis, thereby slowing tumor development." (PMID 36276846, 2022). "In this research, we confirmed that the KDM3A-SP1 axis-mediated PFKFB4 upregulation promoted aerobic glycolysis in OS and augmented tumor cell growth and metastasis." (PMID 35590288, 2022). "Here we have shown that PFKFB4 silencing greatly attenuates tumor growth in an orthotopic xenograft mouse model using patient derived GSCs, dramatically increasing survival." (PMID 36115843, 2022). "Combining currently used chemotherapeutics (conventional or tumor pathway-specific agents) with PFKFB3 or PFKFB4 inhibitors is expected to enrich the range of treatment options." (PMID 33671514, 2021). "Researchers have demonstrated the function of PFKFB4 in tumor growth by showing that silencing the gene inhibits the growth of human lung adenocarcinoma xenografts in athymic mice." (PMID 34211613, 2021). "In the current study, we have shown that PFKFB4 plays a role not only in tumor development of ccRCC but also assist acquisition of Sunitinib-resistance phenotype." (PMID 34593007, 2021). "Since previous studies have demonstrated that the PFKFB4 gene is expressed in many tumor cell lines derived from different tissues, we provide consistent evidence that the testis isoform of the PFKFB protein is also expressed in TNBC cells." (PMID 34211613, 2021). "First, we assessed the expression level of PFKFB4 in tumor tissue specimens by immunohistochemistry and evaluated its prognostic value." (PMID 34211613, 2021). "Numerous studies have demonstrated the importance of PFKFB4 in cell malignancy, and depletion of PFKFB4 was shown to inhibit tumor growth in a xenograft model." (PMID 34211613, 2021). "In this regard, it should also be mentioned that other PFKFB isoenzymes, especially PFKFB4, shape the adaptation of tumor cell metabolism." (PMID 34234350, 2021). "The Cox regression model showed that higher tumor grade, advanced pathological stage and higher PFKFB4 expression were independent prognostic factors, respectively." (PMID 34593007, 2021). "Among them, PFKFB3 and PFKFB4 protein expression is important in tumor cell proliferation and survival." (PMID 33803236, 2021). "In the 19 paired ccRCC samples that underwent microarray, we not only observed significantly overexpressed PFKFB4 but also detected substantial increased protein level of PFKFB4 in tumor than in adjacent kidney tissue." (PMID 34593007, 2021). "Despite fewer studies on the involvement of PFKFB4, this isozyme also seems to contribute to tumor growth." (PMID 33671514, 2021). "6-Phosphofructo-2-Kinase/Fructose-2,6-Biphosphatase 4 (PFKFB4) was differentially expressed showing significantly higher expression in tumor than in normal kidney." (PMID 34593007, 2021). "To validate the findings, we queried PFKFB4 expression in paired kidney samples in TCGA cohort and found significantly higher expression in tumor tissue." (PMID 34593007, 2021). "Based on current research on PFKFB4, this enzyme regulates glucose metabolism in tumor cells, which has been widely recognized." (PMID 32487245, 2020). "Although PFKFB4 has proven to be a target for anti-tumour drug development, its regulation and activation in vivo is still not clear." (PMID 27769068, 2016).
tumor (continued). "Accordingly, the expression of Ki-67 protein was also unchanged among the tumours in which PFKFB4 was knocked down." (PMID 27769068, 2016). "Accordingly, on-going efforts are directed at understanding the relative roles of PFKFB3 and PFKFB4, and at examining the anti-tumor effects of dual Pfkfb3 and Pfkfb4 genomic deletion as well as combined PFK-158 and 5MPN administration." (PMID 26221874, 2015). "Taken together, these in vivo studies provide strong evidence that PFKFB4 supports tumor growth by functioning as a kinase to synthesize F2,6BP." (PMID 25115398, 2014). "The association of PPARGC1B (a PPARγ coactivator) with favorable prognosis suggests that enhancing lipid catabolism may counteract tumor growth, whereas PFKFB4-mediated pentose phosphate flux promotes lipogenesis, driving aggressiveness." (PMID 41364140, 2025). "PFKFB4 is induced under hypoxic conditions and regulates the metabolic flow of glycolysis and the pentose phosphate pathway by balancing the synthesis and degradation of F2,6BP, supporting redox homeostasis and the biosynthetic needs of tumor cells." (PMID 40438141, 2025). "Tumour growth curves indicated that PFKFB4 enhanced the drug resistance of BC cells to palbociclib." (PMID 36127291, 2023). "PFKFB4, as a glycolytic regulator, may play a role in determining the response of tumor cells to 5-FU treatment." (PMID 37770581, 2023). "Therefore, we considered that PFKFB4 plays a key role in tumour development during palbociclib treatment." (PMID 36127291, 2023). "Likewise, the knockdown of PFKFB4 remarkably improved drug sensitivity and enhanced the response of BC cells to palbociclib, which led to decreased tumour volume and weight." (PMID 36127291, 2023). "Thus, additional studies are needed to explore the protein levels of phosphorylated PFKFB3 and PFKFB4 in tumor tissues of OSCC patients." (PMID 37919747, 2023). "Also, injection of HOS cells overexpressing PFKFB4 through the tail vein significantly increased the tumor infiltration in mouse lung tissues." (PMID 35590288, 2022). "Furthermore, we analyzed the correlations between PFKFB4 expression and pathological stages in several tumor types." (PMID 35902861, 2022). "However, PFKFB4 was also involved in tumor progression through redox homeostasis, transcriptional regulation, autophagy and so on." (PMID 32487245, 2020). "Therefore, the results of that study couple the enzyme PFKFB4, an effector of the Warburg pathway, with tumor aggressiveness." (PMID 31139559, 2019). "Taken together, these results support a key function of PFKFB4 in tumour growth and progression." (PMID 27769068, 2016). "To investigate this hypothesis further, we analysed the expression of effector cell proliferation marker (Ki67) and PFKFB4 mRNA within the tumours of 373 HCC patients (data obtained from The Cancer Genome Atlas [TCGA])." (PMID 27769068, 2016). "In addition, we examined uptake of [18F]-FDG in PFKFB4 shRNA and control tumors by PET scan and observed reduced tumor [18F]-FDG uptake in the PFKFB4 shRNA tumors as has also been described as a result of PFKFB3 inhibition." (PMID 25115398, 2014). "Moreover, PFKFB4 expression was significantly higher in the tumour tissues and may be helpful to discriminate tumours from normal and/or premalignant tissue." (PMID 40535577, 2025). "Furthermore, the PFKFB4‐targeted nanoparticle co‐delivery system induces immunogenic cell death in tumor cells, leading to the secretion of relevant cytokines and activation of the JAK‐STAT signaling pathway in DCs and tumor‐associated macrophages (TAMs)." (PMID 40213972, 2025). "Importantly, these data indicate that simultaneous Pfkfb3 and Pfkfb4 deletion and/or inhibition may significantly inhibit tumor growth, which is a focus of ongoing studies." (PMID 39001392, 2024).
tumor (continued). "In addition, knockdown of EZH2 impeded tumor growth through the FBXL7/PFKFB4 axis." (PMID 37179372, 2023). "Hence, we speculate that PFKFB4 plays a prominent role in tumour cell stemness transformation and acquired CDK4/6 inhibitor resistance and targeting PFKFB4 might be an ideal strategy for ER+ BC chemotherapy." (PMID 36127291, 2023). "However, when the disease progresses to an advanced stage, PFKFB4 may begin to play a role in promoting tumor progression, resulting in a lower prognostic value for post-progression survival." (PMID 37770581, 2023). "Furthermore, PFKFB4 is involved in regulating the cell cycle, autophagy, and tumor metastasis." (PMID 37770581, 2023). "Furthermore, HIF1α-induced PFKFB4 mRNA expression correlates with glioma tumor grade." (PMID 30234009, 2018). "To further determine PFKFB4 expression in SCLC, we collected tumor and adjacent non‐tumor tissues from three SCLC patients and analyzed PFKFB4 protein expression using IHC." (PMID 40213972, 2025). "We previously have determined that the PFKFB4 enzyme is co-expressed with PFKFB3 in lung tumors and multiple other tumor types and additionally have observed an increase in PFKFB4 expression when PFKFB3 was silenced." (PMID 39001392, 2024). "Based on the presence and high expression of PFKFB4 in these lung tumors and the longer period of decreased PFKFB3 expression, we speculate that PFKFB4 may compensate for the loss of PFKFB3 to support cell cycle progression, proliferation, and tumor growth in this model." (PMID 39001392, 2024). "In subcutaneous tumor models, THOC3 knockdown inhibited the expression of PFKFB4, and THOC3 overexpression increased its level." (PMID 37500615, 2023). "Semi-quantification of PFKFB4 expression in COAD and adjacent normal tissues revealed significantly higher expression in tumor tissues compared to adjacent normal tissues." (PMID 37770581, 2023). "However, PFKFB4 overexpression could rescue the reduction of tumor growth." (PMID 37500615, 2023). "We found that BMX and FYN had lower expression levels in HCC tumour tissues, whereas KPNA2, PFKFB4, and SPP1 had higher expression levels in HCC tumour tissues." (PMID 36873244, 2023). "Tumor volume and weight of mice treated with sh-EZH2 + oe-NC were observed to be reduced while they were increased in the presence of sh-EZH2 + oe-PFKFB4." (PMID 37179372, 2023). "PFKFB4 plays a pivotal role in controlling the metabolic fluxes of the glycolytic and pentose phosphate pathways (PPP), which are the primary mechanisms tumor cells utilize to metabolize glucose." (PMID 37770581, 2023). "In vivo, overexpression of PFKFB4 increased the growth of xenograft tumors formed by HOS cells, and it led to increased tumor weight on day 20 after animal euthanasia." (PMID 35590288, 2022). "Seven genes, PFKFB4, ALDOA, EGLN3, EHHADH, GAPDH, HMGCS2, and ENO2, related to tumor FDG uptake were revealed to have a good prognostic value for survival in HCC." (PMID 35174098, 2022). "PFKFB4 was overexpressed in TNBC cell lines in hypoxic environments, and its overexpression promoted tumor progression in vitro and in vivo." (PMID 34211613, 2021). "Combined SP1/PFKFB4 inhibition demonstrated synergy in tumor suppression without observable toxicity in mice at effective doses." (PMID 40832790, 2025). "Results of rescue experiments indicated that PFKFB4, as the downstream of THOC3, could mediate tumor-promoting effects in LUSC cells." (PMID 37500615, 2023). "Although PFKFB4 has been shown to be an anti‐tumour target, its relationship with chemoresistance is still not clear." (PMID 36127291, 2023). "Of note, FBP1 was reported to be a tumor suppressor constantly deleted in ccRCC that inhibited glycolysis and PPP with direct inhibition of HIF-1α activity, putting FBP1 in the opposite position to PFKFB4." (PMID 34593007, 2021).
tumor (continued). "Although autophagy can be involved in both tumor suppression and tumor promotion, it has been proposed that the downregulation of PFKFB4 (or the inhibition of its kinase activity) can help inhibit the SRC3/Akt/mTOR pathway, and hence direct autophagy to promote apoptosis of tumor cells." (PMID 35056904, 2021). "For instance, CD44v isoform, an alternative splicing variant of CD44 containing v8–v10 exons, was convinced to drive tumor progression and metastasis by promoting BRCA stemness via activating the PDGFRβ/Stat3 cascade and PFKFB4-mediated glucose metabolism despite tumor-suppressing genetic origin." (PMID 30984247, 2019). "Upon knockdown of PFKFB4, tumour volume and tumour weight were not up-regulated by overexpressing either PPARγWT or PPARγSA compared to LacZ." (PMID 27769068, 2016). "Nevertheless in our analysis we only identified PFK1, but not PFKFB4 as essential for tumor progression in vivo." (PMID 25932951, 2015). "Furthermore, expression of PFKFB3, PFKFB4 and PDK1 was decreased by MTG16-expression; these genes are key regulators of glucose metabolism in tumor cells." (PMID 23840896, 2013). "Our results indicate that PFKFB3 (but not PFKFB4) might be involved in tumor growth through regulating G2/M cell cycle progression in OSCC." (PMID 37919747, 2023). "Positive PFKFB4 expression was observed in nearly all tumor and adjacent normal tissues." (PMID 37770581, 2023). "Whereas silencing PFKFB4 showed potent inhibition in ccRCC cells regardless of HIF1A status, PFKFB4-OE did not per se promote tumor growth." (PMID 34593007, 2021). "PFKFB4 and VEGFA, on the other hand, were not evaluated in tumor specimens because of the variability and unpredictability of their expression in response to hypoxia in the three NB cell lines examined." (PMID 29117193, 2017). "Moreover, the expression levels of KPNA2, PFKFB4, and SPP1 in HCC tumour tissues were significantly higher than those in adjacent normal tissues." (PMID 36873244, 2023).
infection (3 papers, 2022). The state of being infected such as from the introduction of a foreign agent such as serum, vaccine, antigenic substance or organism. "Among the highly upregulated genes in both infection groups were ESPL1, DOCK8, ARID3A, PFKFB4, ANKZF1, BANP and GRB7, all of which exhibited a log2 fold change of ≥1.5." (PMID 37193047, 2022).
adenocarcinoma (2 papers, 2017 to 2020). A common cancer characterized by the presence of malignant glandular cells. "In the present study, PFKFB4 expression increased significantly with androgen-independent growth, suggesting that PFKFB4 is involved in the behavior of PCa cells during the phenotypic switch from adenocarcinoma to CRPC." (PMID 32487245, 2020).
PFKFB4 also shares sentences with these, for which no sentence is quoted: non-small cell lung carcinoma (3 papers); acute myeloid leukemia (2); lung squamous cell carcinoma (2); sarcoma (2); triple-negative breast carcinoma (2); acute monocytic leukaemia (1); colorectal cancer (1); gallbladder cancer (1); malignant glioma (1); mastitis (1); multiple myeloma (1); Obesity (1); osteosarcoma (1); premature ovarian failure (1); viral infections (1).